MICB (MHC class I polypeptide-related sequence B)
Diseases named in the same sentence as MICB in open-access papers (continued):
Sharing a sentence is not in itself a finding about the gene and the disease.
reovirus infection (1 paper, 2023). "Finally, as shedding of NKG2D ligands is a well-described immune evasion mechanism of tumor cells we also tested MICB shedding, which was reduced after reovirus infection." (PMID 37753084, 2023). "To uncover the mechanism by which reovirus infection leads to the reduced expression of MICA, MICB, ULBP2, and ULBP3 in infected cells, we first evaluated their shedding from the cell surface." (PMID 37753084, 2023). "Thus, we further tested whether the intracellular protein levels of MICA, MICB, ULBP2, and ULBP3 were altered upon reovirus infection." (PMID 37753084, 2023).
Sepsis (1 paper, 2017). Sepsis is defined as life-threatening organ dysfunction caused by a dysregulated host response to infection. "MICB, PSMB2, PSMB8 and PSME2 showed consistently low level of expression in melioidosis cohort irrespective of other factors like comorbidities (risk factors), duration of clinical symptoms and antibiotic treatment, compared to other sepsis controls." (PMID 28628607, 2017). "MICB, PSMB2, PSMB8 and PSME2 were significantly up regulated in other sepsis cases compared to healthy controls while these target genes showed no significant differential expression in patients suffering from melioidosis compared to healthy controls." (PMID 28628607, 2017).
Thrombocytopenia (1 paper, 2023). A reduction in the number of circulating thrombocytes. "A genetic study reported associations of genetic polymorphisms (the R/R genotype of FCGR2A p.R131H and the G/G genotype of CCL2 c.-2518 A > G) with thrombocytopenia; however, our study did not reveal an association of MICB and PLCE1 variants with thrombocytopenia." (PMID 37958261, 2023).
triple-negative breast carcinoma (1 paper, 2025). An invasive breast carcinoma which is negative for expression of estrogen receptor (ER), progesterone receptor (PR), and human epidermal growth factor receptor 2 (HER2). "This interaction alters the expression of miR-34a and miR-17–5p and modulates MICA//MICB (MHC class I-related chain A and B), PDL1 (programmed death ligand-1), and B7-H4 (member of B7 family) expression on triple-negative breast cancer cells." (PMID 40863726, 2025).
Varicose veins (1 paper, 2020). Enlarged and tortuous veins. "The analysis of the genetic basis of varicose veins demonstrates the power of the platform for generating new biologicalhypotheses such as, for example, ours postulating a causal relationship between the levels of the proteins MICB andCD209 in blood and the risk for this disease." (PMID 35088001, 2020).
ZIKV infection (1 paper, 2019). "Moreover, ZIKV infection was able to increase the expression on A549 cells of NKG2D ligands (NKG2DLs), namely MICA, MICB, and ULBP2, at both the mRNA and protein levels, suggesting the possible involvement of these molecules in the recognition by NKG2D-expressing Vδ2 T-cells." (PMID 31547470, 2019).
tumor (230 papers, 2010 to 2026). "Factors such as genetic polymorphisms, tumor type, and disease stage can lead to heterogeneous MICB expression." (PMID 40670925, 2025). "Proteolytic shedding of MICA and MICB caused by tumor evasion promotes tumor progression, which is usually alleviated by antibody-mediated inhibition to restore the NK-driven innate immunity." (PMID 38673829, 2024). "A study of MICB expression had shown a significantly high expression that was associated with tumor size and better overall survival." (PMID 37869102, 2023). "Upon the recognition of tumor cells, NK-cell activation occurs through the interaction of NKG2D receptors on the surface of NK cells with ULBP ligands and the MHC class I chain-associated proteins MICA and MICB on the surface of tumor cells." (PMID 36766706, 2023). "High MICB expression was significantly associated with tumor located at proximal colon (P < 0.001) and M0 stage(P = 0.047)." (PMID 32306128, 2020). "The proteolytic shedding of MICA and MICB by tumor cells causes immune escape via downregulation of these NKG2DL." (PMID 33424862, 2020). "For primary cohort, the univariate cox regression analysis showed that preoperative CEA level, tumor location, primary differentiation, T stage, N stage, M stage and MICB expression were significantly associated with OS." (PMID 32306128, 2020). "MICB expression was significantly associated with tumor size and primary histological type in primary cohort, and with primary tumor location and distant metastases in validation cohort." (PMID 32306128, 2020). "Suppression of MICA and MICB decreases the susceptibility of tumor cells to the cytotoxicity of NK cells." (PMID 30046565, 2018). "MICA and MICB expression has been described in a variety of tumors and has been associated with an increased tumor infiltration by Vδ1+ T cells." (PMID 29707004, 2018). "The expression of NKG2D ligands such as MICA and MICB render tumor cells more susceptible to being killed by NK and T cells." (PMID 26902929, 2016). "The metastasis-associated microRNA miR-10b was found to downregulate MICB, thereby impairing the ability of tumor cells to be eliminated by NK killing." (PMID 23269922, 2012). "The present study indicates that Anti-MICB-CAR has been successfully expressed in primary natural killer (NK) cells and secretes free Anti-MICB-scFv and interleukin-15 (IL-15), demonstrating strong tumor-killing ability." (PMID 41516373, 2026). "We designed soluble Anti-MICB-scFv blocks tumor immune evasion targeting the MICB antigen, thereby enhancing CAR-NK cytotoxicity while reactivating endogenous immune attacks against malignancies." (PMID 41516373, 2026). "Reducing the expression of MICB on the surface of tumor cells by hydrolyzing the α3 domain of MICB is one of the important mechanisms by which tumor cells conduct immune escape." (PMID 41516373, 2026). "We investigated the killing ability of Anti-MICB-CAR-NK on five tumor cells with differential MICB expression, PANC-1, A549, HepG2, BxPC-3, and AsPC-1." (PMID 41516373, 2026). "On one hand, the activating NKG2D receptor, which is expressed on the surface of NK cells, recognizes stress-induced ligands including MICA/MICB, that are presented on tumor cells; this recognition event directly triggers a cytotoxic response in NK cells." (PMID 41607548, 2026). "Second, the NK cells are genetically engineered to specifically recognize MICB-expressing tumor cells, thereby enhancing the cytotoxic activity of the infused Anti-MICB-CAR-NK cells." (PMID 41516373, 2026). "Second, the CAR structure is designed to release free Anti-MICB-scFv, which binds to MICB on the surface of distal tumor cells." (PMID 41516373, 2026). "It was confirmed that Anti-MICB-CAR-NK cells significantly enhanced the anti-tumor ability compared to NK cells." (PMID 41516373, 2026). "Anti-MICB-scFv, when targeting the MICBα3 domain, has been shown to bind to MICB proteins on the surface of tumor cells with high efficiency." (PMID 41516373, 2026).
tumor (continued). "The IHC results reveal that Anti-MICB-CAR-NK cells show a more pronounced ability to infiltrate the tumor." (PMID 41516373, 2026). "Anti-MICB-CAR-NK cells exhibit strong cytotoxic activity against tumor cells with high MICB expression." (PMID 41516373, 2026). "Anti-MICB-CAR-NK cells activate the tumor-killing ability of NK cells by targeting MICB and preventing MICB shedding; IL-15 enhances the activity of Anti-MICB-CAR-NK cells." (PMID 41516373, 2026). "The PANC-1 xenograft model was established in order to elucidate the anti-tumor effects of Anti-MICB-CAR-NK in vivo." (PMID 41516373, 2026). "For example, the NK Group 2, Member D (NKG2D) receptor can recognize stress ligands such as MHC Class I Chain-Related Proteins A/B (MICA/MICB) present on tumor cells, which prompts the release of perforin and granzyme via the Vav1-PI3K signaling pathway." (PMID 41607548, 2026). "Flow cytometry analysis Anti-MICB-CAR-NK treatment significantly enhanced the apoptotic capacity in PANC-1 tumor cells with high MICB expression compared to AsPC-1 cells with low MICB expression." (PMID 41516373, 2026). "Overall, this study demonstrated that combined neoantigens and shared MICB α3 antigen for tumor vaccination enhances immune efficacy by eliciting ILC1s-mediated tumor pyroptosis and support the rationale and clinical translation for cancer immunotherapy." (PMID 41998137, 2026). "This phenomenon led to an increased binding of tumor cells by secreted Anti-MICB-scFv, subsequently inducing the lysis of tumor cells by immune cells." (PMID 41516373, 2026). "This assertion is supported by compelling evidence, which is the robust anti-tumor efficacy of Anti-MICB-CAR-NK cells." (PMID 41516373, 2026). "The expression of MICB in the tumor tissue of the Anti-MICB-CAR-NK group was significantly higher than that of the NK and NC groups." (PMID 41516373, 2026). "The experimental results demonstrated that the viability of PANC-1 tumor cells was ‌55.55%‌ after treatment with ‌Anti-MICB-CAR-NK cells‌ and the co-culture of ‌Anti-MICB-CAR-NK supernatant + NK cells‌ also significantly reduced the viability of PANC-1 cells." (PMID 41516373, 2026). "Firstly, Anti-MICB-scFv targets the MICB α3 domain to prevent MICB shedding, preventing tumor cells from immune escape and prompting the killing of tumor cells by MICB-CAR-NK." (PMID 41516373, 2026). "This approach aims to simultaneously induce a neoantigen-specific cellular immune response and an anti-MICB α3 humoral immune response, to enhance the recognition and killing of tumor cells by immune cells." (PMID 41998137, 2026). "Tumor cell-platelet interactions also trigger the release of MICA and MICB from the tumor cell membrane into the TME." (PMID 39934930, 2025). "The high expression of MICA and MICB on the surface of various epithelial cell-derived malignant tumors makes them potential therapeutic targets and important mediators of tumor immune escape." (PMID 40563539, 2025). "MICA and MICB on the surface of tumor cell membranes can bind to the NKG2D receptor on the surface of NK cells, activating NK cells to perform cytotoxic effects." (PMID 40563539, 2025). "Regarding human NKG2D ligands, in vitro studies have reported that tumor cells expressing MICA, MICB, or ULBP2 are more susceptible to NK cell-mediated cytotoxicity." (PMID 40243581, 2025). "As important ligand molecules of the NK cell-activating receptor NKG2D, MICA and MICB on the surface of tumor cells activate the anti-tumor effect of NK cells after binding to NKG2D." (PMID 40563539, 2025). "Tumors evade γδT cell-mediated cytotoxicity through several mechanisms, including the downregulation of NKG2D ligands (e.g., MICA, MICB, ULBPs), which are crucial for γδT cells to efficiently recognize and attack tumor cells." (PMID 40226616, 2025).
tumor (continued). "Abnormal expression of metalloproteinases is regulated by HIF-1α, which induces the expression of MMP2, MMP9, ADAM10, etc., in tumor cells, hydrolyzing MICA and MICB on the surface of tumor cells and mediating immune escape." (PMID 40563539, 2025). "Activating receptors, including NKG2D, NKp30, and NKp46, recognize stress-induced ligands (e.g., MICA, MICB) or tumor-specific proteins upregulated on the tumor cell surface." (PMID 40236691, 2025). "Chemotherapy can cause tumor cell stress, leading to the upregulation of stress-induced ligands like MICA and MICB, which are recognized by γδT cells." (PMID 40226616, 2025). "One of the most well-characterized NKRs expressed on γδT cells is NKG2D, which binds to MICA, MICB, and ULBPs, stress-induced ligands commonly upregulated in tumor cells." (PMID 40226616, 2025). "Previous studies have also evaluated the immunological effects of human NKG2D ligands, such as MICA and MICB, by expressing them in murine tumor models." (PMID 40558520, 2025). "For instance, proteolytic shedding of MICB from the tumor cell surface can reduce detectable levels, as tumor cells often shed MICA/B proteins to evade immune detection." (PMID 40670925, 2025). "The class 1 HDAC inhibitor, entinostat, has been shown to upregulate MHC-I in NB, resulting in the enhanced cytotoxicity of tumor-specific T cells, and it also increased the expression of MICA/MICB, augmenting NK recognition of tumor cells as well." (PMID 40507292, 2025). "S-palmitoylation enhances the clustering of NK receptors such as NKG2D and 2B4 with their ligands (MICA/MICB) within cholesterol-rich microdomains, optimizing NK cell activation and tumor cell recognition." (PMID 40335986, 2025). "Alternatively, platelet coating reduced surface expression of NKG2D ligands, in particular, MHC class I chain-related sequence A (MICA) and MICB, on tumor cells and thereby diminished NKG2D-dependent lysis of tumor cells." (PMID 40427186, 2025). "Monoclonal antibodies against MICA and MICB can enhance the activation of NK cells and γδT cells, leading to the cytotoxicity of the tumor cells." (PMID 40226616, 2025). "The purpose of tumor cells expressing MICA or MICB is to activate NK cells, γδT cells, or CD8+T cells to kill tumor cells and promote anti-tumor immunity." (PMID 40563539, 2025). "A thorough examination of the TCGA-LIHC and GEO cohort revealed that MICB expression was notably increased in tumor tissues compared to normal tissues." (PMID 38541004, 2024). "Other studies have shown that histone deacetylases (HDACs) inhibitors can induce higher levels of MICA/MICB expression on tumor cells, thus promoting NK cell tumor activity." (PMID 39339180, 2024). "During the early phase of tumor cell formation, activating the MICB/NKG2D signaling pathway leads to the release of several cytokines." (PMID 38541004, 2024). "This specific MICB‐vax vaccine applies the α3 domain of MICB to induces high‐titer antibodies targeting the highly conserved α3 domain, then the antibodies strongly bind to tumor cells expressing human MICB and prevent its shedding." (PMID 38882209, 2024). "The increase in expression of MICA and MICB led to an increase in NK cell-mediated cytotoxicity, leading to tumor growth suppression." (PMID 39161385, 2024). "Vorinostat downregulated microRNA-20a, diminished STAT3 tyrosine phosphorylation, and increased histone acetylation at MICA and MICB promoters, leading to increased expression of these genes and enhanced natural killer (NK) cell-mediated tumor targeting." (PMID 38915093, 2024). "Correlation analysis indicated positive associations of CD160 ligands such as TNFRSF14 and HLA-C, and NKG2D (KLRK1) ligands MICA and MICB with the tumour-infiltrating CD56bright NK and CD8+ TEM cells." (PMID 39877370, 2024).
tumor (continued). "Previous studies have described that Vδ1 γδ T cells recognized stress-induced antigens, such as MHC class I-related chain A (MICA and MICB), expressed on epithelial tumor cells through the ligand, natural killer group member 2-D (NKG2D)." (PMID 38915409, 2024). "Other HDAC inhibitors have been shown to increase the expression of stress-inducing ligands, such as MICA, MICB and ULB-3, on the surface of tumor cells, thereby increasing the susceptibility of these tumor cells to NK cell-mediated cytolysis." (PMID 38254784, 2024). "Remarkably, while MICB TRAMP mice displayed accelerated disease onset compared to TRAMP-only counterparts, mice in which MICB.A2 was co-expressed were largely protected from tumour formation." (PMID 37626965, 2023). "The shed ligands MICA and MICB from the tumor cells directly pair with the NKG2D, leading to NK cell desensitization." (PMID 38041084, 2023). "NK cells recognize tumor cells through their NKG2D receptor binding to its ligand, MHC class I-polypeptide related sequence A or B (MICA/MICB) which are expressed on the surface of tumor cells." (PMID 36830840, 2023). "CD155 and MICA/MICB values oscillated up and down, while HLA-E intensity remained unchanged in infected OvCa tumor digests." (PMID 37949944, 2023). "Another study revealed worse survival of patients with CRC with downregulated MICB because the tumor evades recognition by the immune system." (PMID 37869102, 2023). "Mechanism studies revealed that BCL11B prevents cancer immune evasion by acting as a competitive endogenous RNA to upregulate MICA and MICB, which essentially control tumor immune surveillance." (PMID 35621244, 2023). "NKG2D is a lectin-like type 2 transmembrane receptor mostly expressed by human NK cells and binds to MHC-related ligands such as ULBPs, MICA, and MICB, which are highly expressed in tumor cells but rarely in healthy cells." (PMID 35880177, 2022). "Our findings showed that dramatic downregulation of exosomal PD-L1, E-cadherin, ULBP1, ULBP3, MICA, MICB, Siglec7 and significant upregulation of exosomal PD-1 and IFN-gamma were associated with tumor regression." (PMID 36741391, 2022). "We discover that Entinostat, Decitabine, Ricolinostat and Vorinostat significantly increase MICA and MICB expression on tumour cells and CAFs." (PMID 35731974, 2022). "After exposure to cytotoxic treatment, neoplastic cells upregulate the expression of MICA and MICB, which increases the anti-tumor activity of γδ T cells." (PMID 36499125, 2022). "Among them, blockade of proteolytic shedding of MICA or MICB through genetic engineering or via antibody-dependent metalloproteinase inhibition, restored potent NK cell-mediated killing tumor targets." (PMID 34201655, 2021). "MICA and MICB (Rae1 in mouse) have a key role in the recognition of tumor cells by the innate immune system where their engagement with NKG2D receptors on NK cells triggers NK cell-mediated cytotoxicity." (PMID 33789714, 2021). "MICAB1, targeting MICA and MICB, promoted an efficient tumor target cell lysis by PBMCs when compared to the anti-EGF-R mAb cetuximab and the anti-CD20 mAb rituximab, which are widely used in clinical practice." (PMID 35967081, 2021). "In fact, blocking MICA and MICB shedding from the tumor surface reduced melanoma metastasis and improved the antitumor immunity in an NKG2D- and CD16-dependent manner." (PMID 33802954, 2021). "In this review, we revised data that position MICA and MICB as attractive targets in I-O to leverage NKG2D-dependent NK cell-mediated anti-tumor effects and catalyze tumor immunity." (PMID 34394116, 2021). "Tumor-associated markers can also be detected by receptor–IgG chimeric proteins, such as NKG2D-IgG that binds MICA and MICB, ligands that are upregulated in various malignancies." (PMID 33467027, 2021). "As a matter of fact, MICB overexpression by tumor cells activates cytotoxic lymphocyte functions such as lysis and elimination of cancer cells through NKG2D receptor activation." (PMID 34539626, 2021).